CRP (C-reactive protein)
Diseases named in the same sentence as CRP in open-access papers (continued):
Sharing a sentence is not in itself a finding about the gene and the disease.
leukocytosis (continued). "Blood tests revealed microcytic hypochromic anemia (Hb 9.4 g/dL) with leukocytosis, neutrophilia, thrombocytosis, hypoalbuminemia, with elevated C-Reactive protein (15 mg/dL), erythrocyte sedimentation rate (VS 113 mm/h), fibrinogen and ferritin (1703 ng/mL)." (PMID 36096831, 2022). "On average, elevated ESR level was seen in most of the patients, followed by thrombocytosis, leukocytosis, raised CRP and anaemia." (PMID 35743997, 2022). "Leukocytosis on admission was also observed in complication group (p < 0.001), being paralleled by a trend towards raised CRP (p = 0.20)." (PMID 35053696, 2022). "The patient was febrile on admission, and laboratory investigations showed leukocytosis and elevated C-reactive protein (CRP)." (PMID 36037639, 2022). "Via that inhibitory route, tocilizumab artificially lowers CRP levels and attenuates signs of inflammation, such as fever and leukocytosis." (PMID 36294300, 2022). "Laboratory evaluation revealed leukocytosis, elevated C-reactive protein, hypoalbuminemia, and proteinuria." (PMID 36336675, 2022). "Another score is the AIR—appendicitis inflammatory response—that considers parameters such as vomit, pain in the right iliac fossa, pain degree, fever, neutrophil count, leukocytosis, and CRP." (PMID 36291361, 2022). "The risk factors of CAL in KD patients are as follows: IVIG resistance, anemia, hypoalbuminemia, leukocytosis with predominant neutrophil count, high C-reactive protein (CRP) levels, male sex, and age younger than 1 year or older than 6 years." (PMID 36361563, 2022). "Laboratory findings showed leukocytosis with 21,200/mm3 and elevation of C reactive protein to 21 mg/L, Total bilirubin/direct bilurbin = 86 μmol/L/78 μmol/L, AST/ALT = 128/95." (PMID 35714394, 2022). "Leukocytosis and C-reactive protein levels are useful laboratory markers for evaluating the risk of infection in the absence of fever." (PMID 36064957, 2022). "The duration time of analgesia was significantly longer in study group (p < 0.000001), with CRP values lower on all postoperative days (1, 2 days—p < 0.00001, 3 days—p = 0.00538), and leukocytosis on day 2 (p < 0.0086) and 3 (p < 0.00042)." (PMID 35149701, 2022). "The positive control suffered from microcytic hypochromic anemia, thrombocytopenia, leukocytosis, a decrease in L/N ratio, increased CRP level, severe histopathological changes, and decreased CD4+ expression, and an increase in CD8+ and COX-2 expression." (PMID 35698524, 2022). "Although this study did not perform a comparative analysis between Campylobacter and other bacterial pathogens, older age, abdominal pain, leukocytosis, and high CRP levels were characteristic features in our study." (PMID 36670591, 2022). "The peak values of biochemical analysis showed that leukocytosis, neutrophilia, ferritin, CRP, LDH, FPG and triglycerides are significantly higher in NOD patients (p < 0.05)." (PMID 36293811, 2022). "The most typical laboratory findings are low platelet count, leukocytosis, anemia, and elevated plasma C-reactive protein (CRP) and creatinine levels, as well as hematuria and proteinuria." (PMID 35336910, 2022). "Other criteria are worsening of gas exchange after a period of either improvement on the ventilator or stability, bradycardia or tachycardia (altered hemodynamic), and positive serum biomarkers such as C-reactive protein, procalcitonin or leukocytosis." (PMID 36291475, 2022). "A basic metabolic panel and complete blood count were remarkable for leukocytosis of 23,400/μL with left shift with 8% band form and significant elevation of C-reactive protein (CRP) of 39.57 mg/dL." (PMID 36581904, 2022). "Among blood investigations, leukocytosis (67.9%), raised CRP (33.5%), and leukopenia (28.4%) were the most common abnormalities." (PMID 34570805, 2021).
leukocytosis (continued). "In a previous study, patients with COPD included higher proportions of smokers with elevated CRP, leukocytosis, interleukin (IL)-6, and tumor necrosis factor (TNF)-α levels when compared to patients without COPD." (PMID 34537026, 2021). "His blood tests revealed mild leukocytosis (up to 13 K) and a slightly elevated CRP level (16 mg/L)." (PMID 33804790, 2021). "Laboratory tests conducted on the same daydetected persistence of anemia, leukocytosis, thrombocytosis, besides elevatedC-reactive protein (CRP)." (PMID 32876305, 2021). "Laboratory examinations revealed mild leukocytosis (16.39 × 109/L), increased C-reactive protein (CRP) level (62.08 mg/L) and mild hypoalbuminemia (36.5 g/L)." (PMID 33546043, 2021). "In contrast, patients with endemic HCoV pneumonia presented with bacterial pneumonia, dyspnea, leukocytosis with left shift, and increased CRP at admission." (PMID 33444422, 2021). "The laboratory tests revealed leukocytosis with neutrophilia, elevated C-reactive protein and liver cytolysis." (PMID 33466220, 2021). "Coronary artery disease, connected to atherosclerotic inflammation, and acute coronary syndromes are conditions resulting in the increase of both C Reactive Protein (CRP) levels and leukocytosis." (PMID 33407375, 2021). "The most common laboratory findings at diagnosis in our cohort were elevated acute phase reactants (ESR, 34%; CRP, 32%), followed by leukocytosis (16%)." (PMID 34118940, 2021). "Rates of leukocytosis, neutrophilia, higher D-dimer, ferritin, and highly sensitive C-reactive protein (CRP) were significantly higher in ICU patients." (PMID 34055842, 2021). "Current diagnostics such as leukocytosis, increased serum C-reactive protein (CRP), and abdominal ultrasound (US) imaging have assisted in decreasing the frequency of diagnostic laparoscopies." (PMID 34064691, 2021). "The initial assessment revealed leukocytosis, elevated C-reactive protein, and a significant elevation of amylase and lipase." (PMID 33738152, 2021). "Laboratory results showed microcytic anemia, leukocytosis, thrombocytosis, elevated C-reactive protein and erythrocyte sedimentation rate, and rheumatoid factor (RF) and anti-cyclic citrullinated protein (ACPA) antibody positivity." (PMID 34109188, 2021). "Patients with EVALI presented leukocytosis, elevated erythrocyte sedimentation rate, and high C-reactive protein levels in peripheral blood." (PMID 33924379, 2021). "Leukocytosis was more common than leukopenia, and C-reactive protein levels were >100 mg/L (reference <5 mg/L)." (PMID 34286684, 2021). "Laboratory tests showed leukocytosis (17.93–35.3 × 109/l) and C-reactive protein (CRP: 0.1–11.2 mg/l)." (PMID 33731039, 2021). "Laboratory findings showed leukocytosis (11,900/μl) and elevated C-reactive protein levels (6.18 mg/dl) and serum amyloid A (SAA, 32.5 μg/ml)." (PMID 33685423, 2021). "Significant laboratory findings included an elevated C-reactive protein (CRP) 144 mg/L and leukocytosis (white blood cell count 26.0 × 109/L, with neutrophil count 22.0 × 109/L)." (PMID 34865632, 2021). "The common laboratory changes of patients included lymphopenia, leukocytosis, decreased platelet counts, supraphysiological concentrations of transaminase, C-reactive protein, and D-dimer." (PMID 33258995, 2021). "Laboratory tests showed an increase in CK, CRP, leukocytosis, fibrinogen, and ALT levels in 15, 9, 8, 7, and 4 participants, respectively." (PMID 33841437, 2021). "Systemic inflammatory reactions can be tracked by leukocytosis and release of acute phase proteins (APPs), such as c-reactive protein (CRP) and cytokines." (PMID 34568354, 2021). "Initial tests disclosed leukocytosis, anemia, hypoalbuminemia, an elevation in C-reactive protein and fecal calprotectin." (PMID 34559136, 2021). "Her blood tests disclosed leukocytosis up to 14 K, with a very slight elevation in her CRP level (7.95 mg/L)." (PMID 33804790, 2021).
leukocytosis (continued). "IL-6 is a cytokine that induces fever, leukocytosis, thrombocytosis, chronic disease anemia, and increased acute phase reactants, including CRP, ESR, and serum amyloid A." (PMID 34041254, 2021). "Two days after admission the patient rapidly deteriorated clinically, leukocytosis increased to 34.000/mL and CRP to 490 mg/L, while kidney function decreased with a serum creatinine level of 1.4 mg/dL." (PMID 34068785, 2021). "Initial tests showed anemia, hypoalbuminemia, leukocytosis, an elevation in C-reactive protein (CRP) and fecal calprotectin." (PMID 34559136, 2021). "Blood tests revealed leukocytosis (12.94 × 109/L), increased C-reactive protein (13.3 mg/L), and abnormal D-Dimer concentrations (2.38 mg/L)." (PMID 33400676, 2021). "The reasons for ampicillin-cefotaxime prescription included maternal chorioamnionitis (n = 4), increased levels of maternal C-reactive protein (n = 5), and infant leukopenia or leukocytosis (n = 5)." (PMID 34136438, 2021). "In our study, we found that the presence of leukocytosis, neutrophilia, high levels of highly sensitive CRP, ferritin, D-dimer, and AST at the time of admission were associated with patients' deterioration, ICU admission, and death." (PMID 34055842, 2021). "The results of the laboratory studies of blood seldom show leukocytosis and an increase in serum levels of the classical acute-phase proteins, e.g., CRP or fibrinogen." (PMID 34281177, 2021). "The percentage of patients in the control group with elevated CRP levels on admission was 50% (n=37), leukocytosis was 22% (n = 16)." (PMID 33746874, 2021). "Laboratory tests revealed anemia (hemoglobin level: of 8.0 g/dL), leukocytosis with neutrophilia (21,900 cells/uL), and an elevated C-reactive protein level (8.90 mg/dL)." (PMID 33663072, 2021). "Laboratory work up showed hemoglobin of 12.7 g/dL, leukocytosis of 22,000/L and a C-reactive protein (CRP) of 95 mg/L." (PMID 34068785, 2021). "In our hospital, antibiotic use usually was decided based on clinical signs and laboratory parameters (leukocytosis, increased CRP, or procalcitonin)." (PMID 33868645, 2021). "The monitoring of body temperature, arterial blood pressure, and laboratory markers of inflammation (leukocytosis), c-reactive protein (CRP) level, and possibly the level of procalcitonin is obligatory." (PMID 33532496, 2021). "Here, 7% of cases had a CRP level up to 10 mg/dl (normal value < 0.5 mg/dl), which was accompanied by mild leukocytosis in two (13.1 nl −1, 16.1 nl −1) and elevated temperature (39.1 °C) in one patient." (PMID 34357446, 2021). "Initial observational studies have shown that patients with acute coronary syndromes have elevated inflammatory markers (leukocytosis, neutrophilia, increased erythrocytes sedimentation rate, fibrinogen and C reactive protein [CRP])." (PMID 34180324, 2021). "The patient had leukocytosis and elevated levels of C-reactive protein (CRP) and serum amyloid A (SAA)." (PMID 33685423, 2021). "Blood tests were reported in 16 patients, six patients showed leukocytosis, and one patient showed elevated CRP and CA199." (PMID 34583677, 2021). "Laboratory evaluation on admission revealed leukocytosis, hyponatremia, and elevated C-reactive protein." (PMID 34631173, 2021). "Elevated D-dimers, leukocytosis, and C reactive protein (CRP) were present in most reported cases, and a contrast-enhanced CT exam confirms the vascular thromboembolism and offers important information about the bowel viability." (PMID 35011941, 2021). "All patients showed signs of a systemic inflammatory response at the beginning of EVT with elevated CRP levels frequently accompanied by leukocytosis." (PMID 33593301, 2021). "The investigation revealed that high white blood cells (16x103/ cumm) with neutrophil leukocytosis (80% of white blood cells), elevated C-reactive protein (CRP; 12 mg/dL), and erythrocyte sedimentation rate (40mm/first hour)." (PMID 33575152, 2021).
leukocytosis (continued). "We measured the levels of inflammatory markers (leukocytosis, C-reactive protein—CRP), pain intensity level (visual analog scale—VAS; numerical rating scale—NRS), the life parameters, and noted complications." (PMID 32940751, 2021). "Upon admission, she had had leukocytosis (37,300/μl, normal < 10,000), a high C-reactive protein (59.7 mg/l, normal < 5), and a high lipase (2378 U/ml, normal < 60) and ferritin values (> 2000 ng/ml normal < 100)." (PMID 34050373, 2021). "We mention that 23.3% of cervical cultures had pathogenic germs with the highest prevalence of Escherichia coli, 32.9% of patients had leukocytosis and 14.1% had CRP values above the laboratory’s reference range." (PMID 35011954, 2021). "Laboratory tests performed at admission showed leukocytosis (WBCs, 24,570/μL; neutrophils, 88.5%) and an elevated CRP level (1.74 mg/dL)." (PMID 34021462, 2021). "From a laboratory perspective, 15 had elevated CK levels, nine showed increased CRP levels, eight had leukocytosis, seven showed increased fibrinogen levels, and four showed increased ALT levels." (PMID 33841437, 2021). "Previous studies have shown that elevated inflammatory markers such as ESR, CRP, and leukocytosis are significant predictors of positive findings in patients with CAP." (PMID 34829470, 2021). "In systemic arthritis, anaemia (19%), leukocytosis (38%), thrombocytosis (36%), and elevated acute phase reactants (CRP, 75%; ESR, 66%) were observed." (PMID 34118940, 2021). "Blood analyses revealed evidence of leukocytosis (15.53 * 109/L) and elevated C-reactive protein (CRP) levels (168 mg/L), while procalcitonin (PCT) levels were within the normal range (0.67 ng/mL)." (PMID 34930148, 2021). "Current inflammatory markers of leukocytosis and CRP are too vague to accurately determine appendicitis with high specificity or sensitivity." (PMID 34064691, 2021). "Among patients in whom laboratory tests were ordered, some laboratory abnormalities were observed (e.g., leukocytosis and elevated levels of CRP, lactic acid, cTnI, and D-dimer)." (PMID 35047534, 2021). "She subsequently exhibited prominent leukocytosis and an increased level of C-reactive protein, suggesting markedly increased cytokine levels." (PMID 33996612, 2021). "The laboratory findings included elevated high C­reactive protein (CRP, 335.2 mg/l), leukocytosis (18.96 × 103/μl with neutrophilia (84%), anemia (8.6 g/dl), thrombocytosis (470 × 103/μl) and elevated serum ferritin (2923 ng/ml)." (PMID 34544497, 2021). "In the present material, the analysis focused on such selected inflammatory markers as leukocytosis, and blood and wound drainage fluid CRP levels." (PMID 32940751, 2021). "Laboratory data revealed leukocytosis with a left shift and thrombocytopenia, and showed increased levels of hemoglobin, CRP, D‐dimer, LDH, lactate and renal function parameters; urinalysis demonstrated hematuria and proteinuria." (PMID 34402989, 2021). "The most common laboratory results were leukocytosis (n = 8), increased liver enzymes (n = 6), elevated CRP (n = 5), and thrombocytopenia (n = 4)." (PMID 33718763, 2021). "A 23-year-old Chinese Han man presented with recurrent fever for 18 years and vesiculopustular rashes for 9 years, along with chronic bronchitis, leukocytosis, increased C-reactive protein, immunodeficiency and high serum IgE." (PMID 34093563, 2021). "Among the analytical results, the most relevant were elevated procalcitonin levels, the neutrophil count, the degree of leukocytosis, and elevated C-reactive protein (CRP) levels." (PMID 34749645, 2021). "C-reactive protein (CRP) was raised in 16 patients (80%), leukocytosis was present in 3 patients (13.63%), and thrombocytosis in 8/22 patients (36.3%)." (PMID 34039395, 2021). "Blood analysis revealed elevated C-reactive protein levels in 84.81% of patients and leukocytosis in 54.6%." (PMID 34099754, 2021).
leukocytosis (continued). "Blood tests showed an increase in C-reactive protein and leukocytosis (white blood cell count; neutrophils; lymphocytes; monocytes)." (PMID 34205612, 2021). "All the patients showed certain abnormalities in these parameters during their hospitalization, among which leukocytosis and the elevation of C-reactive protein and D-dimer were the most prominent." (PMID 34956212, 2021). "Inflammatory indicators include leukocytosis, C-reactive protein, and procalcitonin, all of which were increased." (PMID 34926395, 2021). "Lymphopenia and leukocytosis were reported in 2 studies, anemia and elevated C-Reactive Protein (CRP) in 3 studies." (PMID 34379700, 2021). "Increased CRP levels and leukocytosis are markers of infection severity and are related to increased mortality." (PMID 34521357, 2021). "Forty-three percent up to 76% of transplanted patients with AA had leukocytosis, fever, or migrating pain, but all patients had elevated CRP." (PMID 34372902, 2021). "In summary, elevated CRP levels, leukocytosis and granulocytosis were observed in patients with cfDNAhigh levels." (PMID 32443763, 2020). "The APR coincides with infection or tissue injury and is usually a systemic reaction involving fever, leukocytosis and increased serum levels of acute phase proteins (APPs), CRP and serum amyloid components." (PMID 32932765, 2020). "The C-reactive protein and procalcitonin were elevated at significantly in the initial phase of the infection,and they had leukocytosis or leukopenia." (PMID 32938420, 2020). "Among the laboratory parameters, leukocytosis was common (70.3%), and all patients had elevated serum C-reactive protein levels." (PMID 32266189, 2020). "Immediately after surgery, the paraneoplastic symptoms of fever, cough, night sweats, high inflammatory values (CRP up to 20.9 mg/dl), and extreme leukocytosis (up to 100.370/μl) completely declined within hours." (PMID 32072333, 2020). "Two SAEs were documented during the study: one in a Mobilan-treated patient in cohort 1 (severe pollakiuria with leukocytosis and elevated C-reactive protein level) and one in a Mobilan-treated patient in cohort 2 (acute prostatitis)." (PMID 32292576, 2020). "Severe anemia, leukocytosis, thrombocytopenia, and elevated CRP level were demonstrated in pre-hospital laboratory tests." (PMID 32010610, 2020). "Labs will show leukocytosis with a neutrophil predominance and elevated C-reactive protein (CRP); additionally, there can be signs of organ failure based on where metastatic septic emboli spread to." (PMID 32742884, 2020). "Ninety-nine (57%) patients had a combination of elevated CRP, leukocytosis (or leukopenia), and neutrophilia." (PMID 33133811, 2020). "Previous reports have described patients with IMT showing chronic inflammation such as leukocytosis, elevated platelet count, hypergammaglobulinemia, increase of erythrocyte sedimentation rate, and C-reactive protein." (PMID 32430041, 2020). "In SEA, inflammatory findings such as leukocytosis, elevated serum C-reactive protein (CRP) levels, and increased erythrocyte sedimentation rates (ESR) are noted." (PMID 33324773, 2020). "Marked leukocytosis and increase in D-dimer, C-reactive protein, IL-6, and procalcitonin levels developed." (PMID 32607684, 2020). "Her blood workup had worsened, with leukocytosis (13.5 × 103/μl), left shift (83.9% neutrophils), and elevated CRP (24 mg/L)." (PMID 32921316, 2020). "Laboratory abnormalities were significant for anemia, leukocytosis, elevated CRP, and elevated serum IgE levels in both patients." (PMID 37206599, 2020). "The patient's laboratory results showed leukocytosis and elevated C-reactive protein (CRP); thus, the physicians decided to perform a computed tomography (CT) scan." (PMID 31914016, 2020). "Laboratory test results were 49.8% for lymphopenia, 47.7% for leukocytosis, 83.7% for elevated neutrophil ratio, 57% for elevated C-reactive protein, and 71.4% for decreased lymphocyte ratio." (PMID 33426411, 2020).